MUC1 (mucin 1, cell surface associated)
Diseases named in the same sentence as MUC1 in open-access papers (continued):
Sharing a sentence is not in itself a finding about the gene and the disease.
cancer (continued). "Moreover, IL-17RB transcriptionally up-regulates expression of MUC1 and MUC4 to enhance cancer stem-like properties and resistance to gemcitabine." (PMID 33082357, 2020). "An anti‐MUC1 ADC was synthesized by conjugating GSTA neoantigen‐specific 16A with monomethyl auristatin E (MMAE), which displayed potent antitumoral efficacy with an IC50 ranging 0.2–49.4 nM toward various cancer cells." (PMID 33084221, 2020). "MUC1-014E showed sharp and specific staining of carcinoma cells, but no staining in fibroblasts, endothelial cells, and inflammatory cells." (PMID 33167508, 2020). "In addition, MUC1 regulates DNA methylation by upregulating the expression of DNMT1 and DNMT3b methyltransferases in human carcinoma cells." (PMID 33060563, 2020). "Similarly to MUC1 and MUC4, MUC16 overexpression in cancer promotes EMT, cell proliferation, migration and metastasis." (PMID 31514468, 2019). "MUC1, another SEA-type transmembrane mucin, has been studied in much greater detail than MUC17 due to its potential role in the onset and progression of various cancers." (PMID 31387973, 2019). "Interestingly, several well-known cancer biomarkers, THBS1, ENO1, and MUC1, were found to be expressed at much higher abundance in exosomes than total membrane proteins." (PMID 30646616, 2019). "MUC1 was processed and presented to CD8+ T-cells, and primed them for advanced cancer immunity." (PMID 30691225, 2019). "Clinical trials performed with MUC1 vaccines in patients with cancer showed an excellent safety profile with no sign of autoimmunity or serious side effects and encouraging results for less immunosuppressed patients." (PMID 31214178, 2019). "Superiority of this form of MUC1 over carbohydrate antigen 19-9 (CA19-9) and CEA was proven, when used for the purpose of differential diagnostics of benign and malignant diseases of the biliary pathways, as well as for stage I and II carcinomas." (PMID 30875782, 2019). "The lack of effective MUC1-specific T cells in cancer patients is considered a major obstacle in generating an effective antitumor immunity." (PMID 29558459, 2018). "Additionally, mucin-1 (MUC-1), commonly used as a biomarker to evaluate BC recurrence and treatment response, has been suggested to mediate cancer cell dissemination." (PMID 30105032, 2018). "It is interesting to note that MUC4 expression is not correlated with MUC1 that is a major membrane-bound mucin commonly overexpressed in cancer." (PMID 30236127, 2018). "Targeting of MUC1 inhibits EGFR signaling and reduces EGFR-mediated cancer growth." (PMID 29987260, 2018). "Another MUC1 aptamer, labelled with Cy3 dye, has been investigated in 3D cell aggregates (multicellular spheroids of MCF-7 cells) and compared to an anti-MUC1 antibody for its capacity to visualize cancer cells." (PMID 29261171, 2017). "Relative to other TNBC subtypes, claudin-low is characterized by a low expression of epithelial tight-junction claudin proteins, mucin 1 (MUC1), EPCAM and E-cadherin (CDH1), and high expression of epithelial-to-mesenchymal transition (EMT) markers, along with cancer stem cell (CSC) characteristics." (PMID 28235006, 2017). "Notably, MUC1 has been reported to be overexpressed in a variety of epithelial cancers, including SCCHN, and also plays a key role in cancer." (PMID 28038473, 2017). "After establishing the link between decreased levels of MUC-1 and NF-κB in M2-TAM polarization following pterostilbene treatment, we sought to further elucidate MUC-1′s role in promoting tumorigenesis and cancer stemness in NSCLC by silencing Muc1 expression in THP-1 cells." (PMID 27276704, 2016). "Taken together, these analyses confirm endogenous MUC1-ARF protein in human cancer cell lines known to express the MUC1 gene, and conversely the absence of MUC1-ARF protein in cells that do not express the MUC1 gene." (PMID 27768738, 2016).
cancer (continued). "Apt-Td-Dox, however, generated significantly greater cytotoxicity against the MUC1-positive cancer cells versus MUC1-negative control cells." (PMID 27203221, 2016). "Moreover, the PCA3-3STA is more specific for PCa cells than are the previously introduced MUC1, PSA, PEG-3 and hTERT promoter-based expression systems that can be active in many tissues or cancer subtypes." (PMID 26594800, 2016). "The clinical significance of this data is not yet implicit but it certainly points to the cancer specificity of the native MUC1 peptide and perhaps suggests immune tolerance to native MUC1 in the normal individuals." (PMID 27367740, 2016). "Chemotherapy induces cancer cell apoptosis; our previous research indicated that chemotherapy-induced apoptosis may activate cancer stem-like cells (CD44+/CD24−) in MCF-7 and that upregulation of MUC1 occurred." (PMID 26016502, 2015). "In contrast, the remnant cancer nests in PMSB groups have gradually retrogressed via cytolysis, karyorrhexis and pyknosis, with significant NK congregating and extensive macrophage infiltrating yet very sparse MUC-1+ cells surviving." (PMID 26512920, 2015). "They found that, although vaccines containing CpG could induce MUC1-specific antibodies, those antibodies were less efficient at inducing ADCC against cancer cell lines than antibodies raised against Pam3Cys-containing vaccines." (PMID 26557640, 2015). "We then investigated whether brachyury-, MUC1-, and CEA-specific human T cells generated using DCs infected with Tri-Ad5 could lyse human carcinoma cells that endogenously express these TAAs." (PMID 26374823, 2015). "Data from this study furthers our understanding of the mechanisms by which the combination treatment was effective and provides further rationale for designing clinical trials targeting MUC1 and COX signaling pathways to overcome cancer mediated immune suppression." (PMID 24605110, 2014). "Although several papers have connected the altered expression of MUC1 to epithelial–mesenchymal transition (EMT), the impact of atypical O-glycans carried by MUC1 on cancer cells undergoing EMT is still unknown." (PMID 24724053, 2014). "To find out whether a relation between the expression of prominin-1 and other cancer markers such as CEA and MUC1 exists, we re-examined our samples with specific and characterized antibodies." (PMID 24911657, 2014). "Exposure to radiation induced significant cell-surface expression of MHC I (3/3 cell lines), ICAM-1 (3/3), CEA (2/3), and MUC-1 (3/3), regardless of carcinoma type." (PMID 24480782, 2014). "All of these results suggest that a non-MHC-restricted, hypoglycosylated, MUC1-specific T-cell response can be present spontaneously in cancer patients." (PMID 23509794, 2013). "In addition, MUC1 specifically binds to ICAM-1 on the surface of endothelial cells, increasing the adhesion between heterogeneous cells and leading to invasion of the cancer cells into the vascular wall with subsequent metastasis." (PMID 23708102, 2013). "NOTCH1 correlated with the expression of various other cancer-related proteins like HIF1A but not with MUC1 as a marker of normal lung physiology." (PMID 23028920, 2012). "Other approaches against MUC1, rather than molecule vaccines, are also in trials in patients with specific types of cancer." (PMID 24970145, 2012). "Many potential TAAs in MM have been investigated including polymorphic epithelial mucin (MUC1), human telomerase reverse transcriptase (hTERT), PRAME, HM1.24, SP17, Wilms' tumor I (WTI), Dickkopf-1 (DKK1), or member of cancer germ-like family (MAGE, GAGE, BAGE, LAGE, NY-ESO-1)." (PMID 22481968, 2012). "Our findings may have implications for the use and future design of targeted therapies in cancers known to express EGFR, Src, or MUC1." (PMID 22586492, 2012). "MUC1 was expressed in 51 (81.0%), and MUC2 was expressed in 18 (28.6%) carcinomas." (PMID 23101681, 2012).
cancer (continued). "Unlike normal cells, most carcinomas overexpress MUC1, and MUC1 is distributed over the entire cell surface." (PMID 23023583, 2012). "It incorporates the MUC1 antigen, which is overexpressed in the majority of cancers, into a non-propagative pox viral vector, MVA." (PMID 24212823, 2011). "Further, MUC1 expression was found on the surface of CFPAC-1, PANC-1 and CAPAN-1 cancer cells." (PMID 24212784, 2011). "MUC1 is a large molecular weight transmembrane glycoprotein that is overexpressed in many carcinomas including EOC, and mediates signal transduction events that stimulate the motility, invasion, and metastasis of cancer cells." (PMID 21931707, 2011). "Recently, a peptide-based therapy using MUC1 protein transduction domain PTD4 (PMIP), which targets MUC1, EGFR and β-catenin interaction, displayed great efficiency in xenografted and transgenic mice models and inhibits cancer progression." (PMID 24281201, 2010). "MUC1 gene expression is regulated by a tightly related combination of DNA methylation and histone modification via histone H3 lysine 9 (H3-K9) in the 5'-flanking region of the MUC1 promoter in cancer cell lines including HPAFII (MUC1+), BxPC3 (MUC1+), PANC1 (MUC1+/–) pancreatic cell lines." (PMID 24281201, 2010). "One of the molecular markers, such as MUC1 or HER2, might be overexpressed in activated leukocytes present only in cancer patient blood." (PMID 19589136, 2009). "Other antibodies directed against the mucins MUC1, MUC2 and MUC4 should also be evaluated, since these proteins are heavily glycosylated, and altered glycosylation in cancer may influence the reactivity to such antibodies." (PMID 19236510, 2009). "As MUC1 therefore represented a candidate MAL2 partner of particular interest, subsequent experiments were performed to confirm MAL2/MUC1 interactions, and examine their significance in breast epithelial and cancer cells." (PMID 19175940, 2009). "MUC1 represented a candidate partner of particular interest, given the fact that it is overexpressed in cancer types where MAL2 overexpression has also been reported, and as MUC1 overexpression contributes to cancer progression through a number of mechanisms." (PMID 19175940, 2009). "If MAL2 similarly regulates MUC1 expression and/or distribution in cancer cells, increased MAL2 levels could alter cancer cell biology in several ways." (PMID 19175940, 2009). "The supernatants from MUC1-positive cancer cells, but not the control cells, generated a strong protein band at approximately 23 kDa that reacted with anti-NM23H1." (PMID 18446242, 2008). "The addition of exogenous NM23 stimulated the growth of the cancer cells in which MUC1 was not suppressed." (PMID 18446242, 2008). "After determining that the major species on the surface of cancer cells and tissues is MUC1* and not the full-length protein, we decided to study the growth characteristics of the cleaved form compared to uncleaved." (PMID 18446242, 2008). "Our study confirms that these components are present as a minor fraction of the MUC1 transcripts in ‘normal’ as well as cancer tissues." (PMID 19238635, 2008). "Patients with MUC1 expression in the carcinoma show significantly lower survival rates than those without MUC1 expression." (PMID 15599383, 2004). "None of the four mRNA markers, CK-18, CEA, hTRT, or MUC-1, was expressed in any of the negative controls, that is lymphocytes from five healthy donors and five lymph nodes obtained from patients without cancer." (PMID 12915877, 2003). "Immunisation of SCID/hu-PBL mice with the fusion protein resulted in increased MUC1-specific cellular immunity suggesting that combined application of MUC1 peptide and IL2 may mediate an effective immunity against MUC1-positive cancer." (PMID 12966437, 2003).
cancer (continued). "Moreover, subgroup analysis in patients with early GC showed that the proportion of early cancer categorized as non-curative resection was two-fold higher in patients with a high level of MUC1 expression compared to those without high MUC1 expression." (PMID 41154387, 2025). "In primary tumors, cytoplasmic or membranous MUC1 did not significantly differ between cases with (n = 16) and without (n = 101) distant metastases, whether analyzing all carcinoma cells or putative AR structures (p = 0.168–0.902)." (PMID 41332218, 2025). "Thus, a positive feedback loop would be established between MUC1 and HIF-1α that may serve as a global metabolic regulator in cancer cells." (PMID 38540735, 2024). "Therefore, vaccines using DCs pulsed with WT1 and MUC1 peptides (WT1/MUC1-DC) may represent a viable and minimally invasive treatment option for a range of cancers." (PMID 39737308, 2024). "Moreover, we knocked down MUC1 and FGF7 in MCA cancer cells and CAFs, respectively." (PMID 38778448, 2024). "The role of MUC1 extracellular domain O-glycosylation on anoikis resistance was investigated in a later study that demonstrated how inhibition of O-glycosylation by suppression of Core 1Gal-transferase (C1GT, T-synthase) expression significantly increased anoikis in MUC1-positive cancer cells." (PMID 38540735, 2024). "However, where an association has been made between increased MUC1 expression and advanced cancer with LN metastases in studies on OSqCc, the same does not hold true according to the current evidence of MUC1 and MUC4 in OAc." (PMID 37958425, 2023). "Cancer vaccines targeting MUC1 have not yet been successfully used in the clinic." (PMID 37894512, 2023). "MUC1 is an abundant constituent of the PCL, where its extracellular domain contributes to airway surface hydration and its cytoplasmic domain has been shown to influence a variety of cellular signaling pathways that modulate the immune response, cell survival, and cancer progression." (PMID 35699372, 2022). "Similar concentrations could also effectively induce apoptosis in MUC1‐positive cancer cells but not in normal cells or MUC1‐negative human cancer cells." (PMID 34694686, 2022). "Targeted nanocarriers (PLA-PEG-Apt/DOX NPs at w/w ratio 10:1) induced higher apoptosis rate (36.3 ± 3.44%) for 24 h in MUC1 positive A-549 cancer cells in compare to non-targeted form (PLA-PEG/DOX NPs at w/w ratio 10:1, 11.37 ± 1.65%) and free DOX (4.35 ± 0.81%)." (PMID 35304550, 2022). "The results showed that the expression of MUC1 in cancer tissues was significantly higher than that in normal tissues (p value = 2.2e−2), and it was significantly higher in lymph node metastasis positive samples than in lymph node metastasis negative (p value = 4.2e−5)." (PMID 35879749, 2022). "These MCs have been used for building a biosensor for the detection of a cancer biomarker, Mucin 1 (MUC1), a membrane protein, achieving a linearity range of 10−3−103 pg mL−1 and a limit of detection (LOD) of 0.29 fg mL−1 which is comparable to the best reported MUC1 sensing platforms." (PMID 34148139, 2021). "However, clinical studies using MUC1 antibodies have so far not resulted in the identification of a potent anti-MUC1 antibody that can be used for cancer treatment." (PMID 34070311, 2021). "The binding of MGL to the truncated glycan structures on MUC1 leads to a defective T-helper (Th) cell-mediated response as well as to a reduction of cytotoxic T lymphocytes (CTLs), which are usually able to recognize foreign antigens presented via MHCI and eliminate cancer cells." (PMID 34638920, 2021). "Moreover, CIM301-1 and CIM301-8 antibodies showed highly preferential binding to CHO cell lines expressing cancer-related MUC1-Tn/STn epitopes over CHO ldlD cell lines expressing non-modified MUC1." (PMID 34070311, 2021). "However, it can be reasonably inferred that MUC1 does not trigger malignant transformation but plays a significant role in generating vital conditions for cancer development." (PMID 33836774, 2021).
cancer (continued). "Although extensive efforts have been made toward the development of anticancer antibodies targeting MUC1, one of the most studied mucins having cancer-relevant immature O-glycans, no anti-MUC1 antibody recognises carbohydrates and the proximal MUC1 peptide region, concurrently." (PMID 34122956, 2020). "Interestingly, the responses to the MUC1 vaccine were observed only in the patients that had not received chemotherapy in conjunction with their radiation treatment for their original cancer treatment prior to recurrence." (PMID 31214178, 2019). "The long-proposed hypothesis that MUC1 peptides serve as noncanonical ligands for MHC Class I may be examined in cancer patients." (PMID 29857542, 2018). "MUC1 and galectin-3 are both commonly over-expressed by solid tumours and their interactive effects on EGFR activation may have an important influence on EGFR-mediated tumourigenesis and cancer progression, and on the effectiveness of EGFR-targeted therapy." (PMID 28731466, 2017). "Mucin 1 (MUC1) and WNT1 inducible signaling pathway protein 1 (WISP1) have been reported to inhibit E-cadherin-mediated cell-cell adhesion, induce the expression of transcription factors (Snail, N-cadherin, ZEB1 and Smad2), and in turn activate EMT in cancer cells." (PMID 28099903, 2017). "Receiver operating characteristic curve analysis showed that WFA-sialylated MUC1 was superior to carbohydrate antigen 19-9 (CA19-9) and carcinoembryonic antigen (CEA) for the diagnosis of benign biliary tract diseases, BTC, and IhCC, as well as for stage I and II carcinomas." (PMID 27358229, 2017). "The authors also reported the high selectivity for MUC1 protein (using mucin 4 and mucin 16 as non-specific proteins) of the proposed aptasensor, with respect to the antibody sandwich-based assay and the ability to detect MUC1 in cancer patient serum samples." (PMID 27490578, 2016). "The role of MUC1 in cancer seems to be controversial and has not been clearly clarified so far." (PMID 26367866, 2015). "Since these chimeric RNAs are easily detected in cancer samples and not in non-cancerous ovaries, they could represent a better biomarker as compared to parental MUC1 for detecting HGSC or to monitor treatment progress." (PMID 26492273, 2015). "Moreover, the PTX-loaded Apt-NPs enhanced in vitro drug delivery and cytotoxicity to MUC1+ cancer cells, as compared with nontargeted NP lacking the MUC1 aptamer." (PMID 22506124, 2012). "Therefore, therapies suppressing MUC1 cleavage, including antagonists of EGFR and Src, might be beneficial in controlling a wide variety of malignant tumors." (PMID 22586492, 2012). "Most previous vaccines have targeted non-glycosylated MUC1, although this might not be the most cancer specific target." (PMID 23189185, 2012). "To assess whether the 72 amino acid MUC1 cytoplasmic domain (MUC1.CD) would localize to the nucleus of carcinoma cells in the absence of EGF, we expressed MUC1.CD fused to GFP and monitored the cells for MUC1 localization." (PMID 22586492, 2012). "Interestingly, whereas EGF-induced carcinoma cell migration on vitronectin is sensitive to Src inhibition as expected, cell migration driven by the MUC1 cytoplasmic domain does not require Src kinase activity." (PMID 22586492, 2012). "We do not know whether MAb C595 can be internalized in cancer cells and trafficked after binding the cell surface MUC1, similar to MAb J591 or how it can inhibit MUC1 signalling via different signalling pathways." (PMID 21931707, 2011). "However, antibodies to the subset of MUC1 glycopeptides were found in a number of the control sera taken from the cohort of women on Guernsey where no cancer developed during 25 to 30 years of follow-up." (PMID 21385452, 2011). "Moreover, the PTX loaded Apt-NPs enhanced in vitro drug delivery and cytotoxicity to MUC1+ cancer cells, as compared with non-targeted nanoparticles that lack the MUC1 aptamer (P<0.01)." (PMID 21912664, 2011).